BMP4 (bone morphogenetic protein 4)
Diseases named in the same sentence as BMP4 in open-access papers (continued):
Sharing a sentence is not in itself a finding about the gene and the disease.
renal hypoplasia (3 papers, 2013 to 2023). Renal hypoplasia is a developmental anomaly in which one or both kidneys (unilateral or bilateral renal hypoplasia, respectively) have a deficit in the number of nephrons and may be small. "It is possible that loss of Ntn1 results in increases in Bmp4 and a subsequent reduction in Gdnf activity, leading to renal hypoplasia." (PMID 37131589, 2023). "Perturbed growth factor signaling within the ST such as haploinsufficiency of bone morphogenetic protein 4 (Bmp4) causes a shift in the UB induction site leading to urinary tract anomalies including ectopic ureters and renal hypoplasia." (PMID 23409123, 2013). "Thus, our observations point at a potential role of Bmp4 dysregulation in renal hypoplasia of Fuzzy−/− mutants, although it is unclear how a disturbance of the PCP pathway alters Bmp4 expression." (PMID 35076510, 2021). "Reduced Bmp4 mRNA expression as seen in Bmp4 heterozygous mice or following disruption of upstream regulators of Bmp4 is strongly associated with urinary tract anomalies such as duplex systems and renal hypoplasia (they have not to our knowledge been tested for VUR)." (PMID 23409123, 2013).
Retinal dystrophy (3 papers, 2009 to 2022). Retinal dystrophy is an abnormality of the retina associated with a hereditary process. "Pathogenic variants of BMP4 have been reported to cause brain malformation, digital anomalies (poly/syndactyly), and retinal dystrophy." (PMID 35571680, 2022).
thyroid cancer (3 papers, 2021 to 2025). "In thyroid cancer, miR-340-5p is upregulated and it promotes tumor cell proliferation through downregulating BMP4." (PMID 34048366, 2021).
acute leukemia (2 papers, 2018 to 2024). A clonal (malignant) hematopoietic disorder with an acute onset, affecting the bone marrow and the peripheral blood. "Since retinoic acid treatment for acute leukemia patients induces terminally differentiated cells and is an effective therapy for those patients, how BMP4 signaling activation would influence mesothelioma would be an attractive question." (PMID 39376629, 2024).
amelogenesis imperfecta (2 papers, 2017 to 2022). Amelogenesis imperfecta (AI) represents a group of developmental conditions affecting the structure and clinical appearance of the enamel of all or nearly all the teeth in a more or less equal manner, and which may be associated with morphologic or biochemical changes elsewhere in the body. "A total of 44 genes [42 genes in mice with single gene mutations and two additional genes (Bmp4 and Stim2) in compound mutant models] were identified in mice as genes associated with amelogenesis imperfecta through the systematic review." (PMID 35401675, 2022). "Conditional deletion of BMP2 and BMP4 using K14-cre mice (which have keratin-14 promoter-driven cre recombinase) resulted in amelogenesis imperfecta caused by downregulation of the removal of enamel matrix protein during maturation." (PMID 29273814, 2017).
asthma (2 papers, 2022 to 2025). "This indicates that with higher expression of BMP4 there is a correlation to reduced lung function that is a consistent finding in asthmatics that experience asthma exacerbations." (PMID 40131902, 2025). "Two other notable genes upregulated by PGAP3 in ASM are BMP4 (FC = 3.12) and SERPINB5 (also known as Maspin, FC = 3.50), which each have studies supporting their potential role in asthma." (PMID 40131902, 2025). "Levels of BMP4 have correlated with FEV1 and FEV1/FVC in asthma, while in vitro studies demonstrate that MMP13 limits bronchial epithelial repair as it is a protease that degrades fibrinogen and matrix proteins essential for epithelial repair." (PMID 40131902, 2025). "Increased levels of BMP4 and BMP7 have been shown to inhibit the differentiation of human lung fibroblasts into myofibroblasts during asthma remodeling and block the production of extracellular matrix proteins by these cells." (PMID 35770504, 2022). "Although the pathways that mediate PGAP3 induced ASM proliferation and contractility are not known, RNA-Sequencing of ASM expressing PGAP3 identified four genes significantly upregulated by PGAP3 that have known relevance with asthma (i.e., GATA3, ALOX5, BMP4, and SERPINB5)." (PMID 40131902, 2025).
atrial septal defect (2 papers, 2019 to 2020). Interauricular communication is a congenital malformation characterized by a communication between the atrial chambers of the heart. "BMP4 alterations are known to be associated with defects in cardiac septation such as atrial septal defect (ASD), VSD, and atrioventricular septal defects (AVSD)." (PMID 30897084, 2019). "Bmp4 is expressed in the DMP and mutations in BMP4 and the BMP receptor Alk2 have been implicated in atrial septal defects and AVSDs." (PMID 32804075, 2020).
bone fibrous dysplasia (2 papers, 2012 to 2013). "Fibrous dysplasia and non-fibrous dysplasia subjects could be clearly separated by differences in the expression of BMP2, BMP4, BMPR1A, BMPR2, and other members of the BMP pathway." (PMID 23230423, 2012).
brain ischemia (2 papers, 2021 to 2022). Diminished or absent blood supply to the brain caused by obstruction (thrombosis or embolism) of an artery resulting in neurologic damage. "Also, a moderate although significant increase in the expression of BMP4 mRNA was observed in subcortical white matter following cerebral ischemia." (PMID 34567109, 2021). "Our screen experiment showed that most BMP family members, including BMP2, BMP4, BMP5, and BMP7 increased transiently at 24 h after brain ischemia." (PMID 34904361, 2022).
brain malformation (2 papers, 2022). "Pathogenic variants in BMP4 are reported in the literature with a broad phenotypic spectrum, including pituitary and brain malformations." (PMID 35633847, 2022).
cardiac ischemia (2 papers, 2023 to 2024). "In summary, this study demonstrates that DNA hypermethylation of the Bmp4 promoter in cardiomyocytes caused by prenatal DEX exposure substantially dampens promoter binding of transcription factor HIF-1α induced by cardiac ischemia and hypoxia." (PMID 36746787, 2023). "In the present study, we further observed that DNA hypermethylation of bone morphogenetic protein 4 (Bmp4) promoter in cardiomyocytes caused by prenatal DEX exposure substantially dampened the binding activity of transcription factor HIF-1α induced by cardiac ischemia." (PMID 36746787, 2023).
chronic obstructive pulmonary disease (2 papers, 2020 to 2022). A chronic and progressive lung disorder characterized by the loss of elasticity of the bronchial tree and the air sacs, destruction of the air sacs wall, thickening of the bronchial wall, and mucous accumulation in the bronchial tree. "Bmp4 is not only critical for lung development but also associated with chronic obstructive pulmonary disease (COPD)." (PMID 36115458, 2022).
COVID-19 (2 papers, 2022). A disease caused by infection with severe acute respiratory syndrome coronavirus 2. "Furthermore, plasma IL-8, IL-6, TNFRSF11B, and CSF EZR levels were allied to severe COVID-19 using the ordinal backward and best linear model, whereas plasma 4E-BP1 and CSF levels of PD-L1, BMP-4, CLEC10A and ROBO2 withstanded using one model only." (PMID 36351919, 2022).
cutaneous melanoma (2 papers, 2013 to 2017). A primary melanoma arising from atypical melanocytes in the skin. "One case-control study showing BMP4 rs17563 increased the expression of BMP4 mRNA and associated with the risk of cutaneous melanoma." (PMID 28574846, 2017).
demyelination (2 papers, 2013 to 2019). "We have previously shown that BMP4 infusion increases numbers of OPCs during cuprizone-induced demyelination, while infusion of Noggin, an endogenenous antagonist of BMP4 increases numbers of mature oligodendrocytes and remyelinated axons following recovery." (PMID 23650566, 2013).
disc degeneration (2 papers, 2022 to 2025). "The contradictory results of using BMP-4 on IVD regeneration between in vitro and in vivo demonstrate that direct BMP-4 injection for disc degeneration-associated human chronic low back pain should not be undertaken." (PMID 36196149, 2022). "Bone morphogenesis-related genes (TGFB2, BMP4, and THBS1) were enriched in NPPCs, suggesting that NPPCs undergo osteogenic differentiation during the progression of disc degeneration in C2." (PMID 40883814, 2025). "Intradiscal injection of a single dose of BMP-4 failed to halt disc degeneration or induce disc regeneration." (PMID 36196149, 2022).
esophageal squamous cell carcinoma (2 papers, 2016 to 2020). Esophageal squamous cell carcinoma (ESCC) is a type of esophageal carcinoma (EC) that can affect any part of the esophagus, but is usually located in the upper or middle third. "In esophageal squamous cell carcinomas, SERPINE2 promotes tumor metastasis by activating bone morphogenetic protein 4 (BMP4)." (PMID 33317533, 2020).
gastric tumors (2 papers, 2019 to 2025). "In the gastric tumors, many of these genes are regulated by ETS2, BMP4, and TGFB1 and by the kinases MAPK1(ERK) and CCNK and the transcription regulators E2F, CBX5, and CCND1." (PMID 31584998, 2019).
geographic atrophy (2 papers, 2017 to 2020). "Additionally, in retinal sections from three donors with geographic atrophy, BMP4 was detected in areas adjacent to RPE loss and in close proximity to the choroidal vasculature." (PMID 32707711, 2020).
glomerulosclerosis (2 papers, 2018 to 2019). A hardening of the kidney glomerulus caused by scarring of the blood vessels. "Consistent with podocyte injury in nephrotic syndrome, which is caused by apoptosis and cell cycle dysfunction, we have reported that BMP4 constitutes a critical molecule that induces glomerulosclerosis in subjects with DN." (PMID 30158674, 2018). "Bmp4 tgm (+) displayed increased BMP4 expression in whole glomeruli, as shown in red and glomerulosclerosis." (PMID 30158674, 2018). "We previously demonstrated that BMP4, as well as TGF-β1, is involved in the process of glomerulosclerosis." (PMID 31150422, 2019).
juvenile idiopathic arthritis (2 papers, 2021 to 2024). Juvenile idiopathic arthritis (JIA) is the term used to describe a group of inflammatory articular disorders of unknown cause that begin before the age of 16 and last over 6 weeks. "The addition of exogenous BMP4 causes JFLS-Ch to restore this chondrocyte-like phenotype, suggesting that JFLS create a microenvironment favorable for endochondral bone formation, thereby contributing to joint growth disturbances in juvenile idiopathic arthritis." (PMID 33980237, 2021).
juvenile polyposis (2 papers, 2011 to 2014). "In juvenile polyposis, changes in the BMP4 gene may precede APC mutations." (PMID 24806485, 2014).
keloid (2 papers, 2022 to 2025). An irregularly shaped, elevated mark on the skin caused by deposits of excessive amounts of collagen during wound healing. "Subsequently, three of these genes (BMP4, POSTN, and WNT5A) were found to be significantly associated with keloids." (PMID 41278551, 2025). "Some studies indicate that BMP4 is closely related to the regrowth of hair follicles, and strategies for regenerating hair follicles could ultimately impact the development and treatment of keloids." (PMID 41278551, 2025). "The validation of the screened hub genes in the GEO dataset revealed that three hub genes—BMP4, POSTN, and WNT5A—were significantly differentially expressed in keloid tissue compared to normal skin tissue." (PMID 41278551, 2025). "Key hub proteins such as SMAD3, BMP4, and WNT5A are centrally positioned, suggesting their potential roles as critical regulators in keloid pathogenesis." (PMID 41278551, 2025). "Nevertheless, PPI network analysis and subsequent validation using the independent GSE158395 dataset consistently identified BMP4, WNT5A, and POSTN as top hub genes significantly upregulated in keloid tissues." (PMID 41278551, 2025). "We found that the expression levels of BMP4, POSTN, and WNT5A were significantly higher in keloid samples compared to control samples, as identified through differential gene screening and validated using an independent dataset." (PMID 41278551, 2025). "In conclusion, our study identifies BMP4, WNT5A, and POSTN as novel and consistently upregulated hub genes in keloids, potentially acting at the nexus of mechanosignaling, inflammation, and matrix remodeling." (PMID 41278551, 2025). "In terms of expression level, BMP4, MSX1, TBX2, SIX1, DLX5, and DLX2 were lowly expressed, while HAND2, IRX1, EDN1, and MEF2C were highly expressed in keloid fibroblasts." (PMID 35047146, 2022).
left ventricular hypertrophy (2 papers, 2015 to 2020). Enlargement of the LEFT VENTRICLE of the heart. "However, the role of BMP4 and its gene polymorphism in the incidence of left ventricular hypertrophy (LVH) in hypertensive patients remains unknown." (PMID 25591903, 2015).
liver cancer (2 papers, 2019 to 2023). An epithelial or non-epithelial malignant neoplasm that arises from the liver. "BMP4 shows a crucial role in glucose metabolism, and its important role in energy metabolism in liver cancer deserves further exploration." (PMID 37443106, 2023). "Our study reveals that BMP4 is highly expressed in liver cancer tissues and promotes glycogen synthesis via the canonical SMAD signaling pathways." (PMID 37443106, 2023). "Liver cancer-associated fibroblasts (CAFs) were shown to secrete cytokines under the activation of endogenous and exogenous BMP4 to enhance invasiveness of liver cancer cells." (PMID 37443106, 2023). "Genes with 5-mC and 5-hmC level changes enriched in these pathways, such as BMP4, HSP90AA1, DAPK3, FADD and CASP8, have been already reported as potential epigenetic biomarkers for liver cancer." (PMID 31337442, 2019).
metastatic melanoma (2 papers, 2009 to 2019). A melanoma that has spread from its primary site to another anatomic site. "So, we concluded that up-regulation of miR-450b and down-regulation of PAX9 and BMP4 were interconnected with the high MMP9 expression in metastatic melanoma cells." (PMID 31569419, 2019).
multiple sclerosis (2 papers, 2019 to 2023). A progressive autoimmune disorder affecting the central nervous system resulting in demyelination. "In addition, clinical and animal studies on multiple sclerosis have shown that BMP4 is strongly overexpressed in microglia/macrophages at the inflammatory lesion site, indicating that microglia/macrophage-originated BMP4 may be highly correlated with inflammation in the CNS." (PMID 36518009, 2023).
Myocardial fibrosis (2 papers, 2022). "Many studies have shown that BMP4 is related to the development of the heart and mediated cardiomyocyte hypertrophy and myocardial fibrosis." (PMID 35953789, 2022).
nonalcoholic fatty liver disease (2 papers, 2022 to 2023). "BMP4 expression was upregulated in patients and mice with nonalcoholic fatty liver disease, and free fatty acid (FFA)-induced HepG2 and LO2 cell lines." (PMID 35477568, 2022).
oligodendroglioma (2 papers, 2021 to 2025). A well-differentiated (WHO grade II), diffusely infiltrating neuroglial tumor, typically located in the cerebral hemispheres. "This is consistent with the use of BMP4 to induce the differentiation of iPSC into astrocytes, with BMP signaling inducing astrocytic differentiation of patient-derived oligodendroglioma cells, and with BMP ligands being present in FBS." (PMID 39919036, 2025). "Finally, we observed a higher level of APOE, BMP4, KCNN3/SK3, and CRYAB proteins in astrocyte-like cells, whereas the IDH1 enzyme appears to be more expressed in oligodendrocyte-like cells in oligodendroglioma." (PMID 33925547, 2021). "Indeed, the mining of two databases indicated significant upregulation of BMP2 in grade II/III oligodendrogliomas and astrocytomas compared to nontumoral tissues; BMP4 was overexpressed in oligodendrogliomas in one database." (PMID 33925547, 2021).
ovarian tumor (2 papers, 2016 to 2022). "Hedgehogs secreted from ovarian tumor cells induce BMP-4 expression in carcinoma-associated mesenchymal stem cells." (PMID 35693928, 2022). "BMP-4 reciprocally increases hedgehog expression in ovarian tumor cells, indicating a positive feedback loop." (PMID 35693928, 2022). "CA-MSC-derived BMP4 reciprocally increases ovarian tumor cell HH expression indicating a positive feedback loop." (PMID 26755648, 2016). "We demonstrate here that ovarian tumor cell-secreted Hedgehog (HH) induces CA-MSC BMP4 expression." (PMID 26755648, 2016).
pheochromocytoma (2 papers, 2013 to 2025). "We have established a human pheochromocytoma precursor cell line that expresses the neuroendocrine marker, chromogranin A, when differentiated in the presence of bone morphogenic protein 4 (BMP4), nerve growth factor (NGF), and dexamethasone." (PMID 23785438, 2013).
pituitary tumor (2 papers, 2018 to 2019). A benign or malignant neoplasm affecting the pituitary gland. "For example, the BMP-4 plays a key role in the initial development of the adenohypophysis and is also active and functionally involved in the differentiation of pituitary tumors, including prolactinomas and Cushing's disease but not in GH-releasing hormone PA." (PMID 30390486, 2018).
retinoblastoma (2 papers, 2015 to 2017). A malignant tumor that originates in the nuclear layer of the retina. "Ongoing studies will reveal further details on the signaling pathway underlying RA/BMP-4 mediated apoptosis induction in retinoblastoma cells and the effects of a combination with chemotherapeutic agents." (PMID 26173116, 2015). "In the study presented, agonist studies revealed that both RARs and RXRs are involved in RA/BMP-4`s apoptosis induction in WERI-Rb1 retinoblastoma cells." (PMID 26173116, 2015). "In the present study, we further investigated the involvement of caspases in RA and RA/BMP-4 induced apoptosis in this retinoblastoma cell line using Boc-D-fmk, a broad spectrum caspase inhibitor." (PMID 26173116, 2015). "Deciphering signaling mechanisms underlying apoptosis induction of RA and BMP-4 in WERI-Rb1 cells, our study provides useful starting-points for future retinoid-based therapy strategies in retinoblastoma." (PMID 26173116, 2015). "Agonist studies revealed that both, RARs and RXRs are involved in RA/BMP-4 mediated apoptosis in WERI-Rb1 retinoblastoma cells." (PMID 26173116, 2015). "We likewise observed a significant, however, additive interaction of RA and BMP4 in the induction of apoptosis in different retinoblastoma cell lines." (PMID 26173116, 2015).
teratocarcinoma (2 papers, 2013 to 2015). A germ cell tumor characterized by the presence of an embryonal carcinoma component and a teratoma component. "Our data indicate that teratocarcinoma cell line PA-1 expressed a basal keratinocyte marker CK14 when cultured on Matrigel in the presence of BMP-4." (PMID 23958497, 2013).